NPC2 (NPC intracellular cholesterol transporter 2)
Diseases named in the same sentence as NPC2 in open-access papers (continued):
Sharing a sentence is not in itself a finding about the gene and the disease.
glioma (3 papers, 2021 to 2026). A benign or malignant brain and spinal cord tumor that arises from glial cells (astrocytes, oligodendrocytes, ependymal cells). "In contrast, the NPC2 gene was found to be significantly upregulated in gliomas; patients with high NPC2 expression had higher levels of immune cell infiltration and were associated with poor clinical outcome." (PMID 41596244, 2026). "It was shown that SubP28 shared many overlapping genes with microglia/macrophage gene sets, and glioma NPC2 & MES conditions." (PMID 35729639, 2022). "We have investigated the association between gene NPC2 expression and GBM tumorigenesis, and the prognosis role of NPC2 by integrating the GBM samples from the GEO dataset with Single-cell RNA sequencing (scRNA-seq) results of H3K27M-glioma cells." (PMID 33777094, 2021). "Our result also showed that NPC2 independently indicated unfavorable prognosis in glioma when adjusted for with patents’ age (p value = 0.04) and alive status (p value = 0.039), which revealed that NPC2 was a robust independent factor for predicting GBM survival." (PMID 33777094, 2021).
GM1 gangliosidosis (3 papers, 2009 to 2017). A rare lysosomal storage disorder characterized biochemically by deficient beta-galactosidase activity and clinically by a wide range of variable neurovisceral, ophthalmological and dysmorphic features. "We reasoned that other lysosomal diseases characterized by cholesterol and GSL accumulation, including NPC disease due to NPC2 deficiency, GM1 gangliosidosis and mucopolysaccharidosis (MPS) type IIIA, might likewise benefit from CD treatment." (PMID 19750228, 2009). "Our finding that CD is beneficial in reducing cholesterol and GSLs in neurons lacking either NPC1 or NPC2 proteins, but not in neurons in GM1 gangliosidosis or MPS IIIA, may be revealing of the importance of cholesterol's mobility in the NPC-affected cell compared with other lysosomal diseases." (PMID 19750228, 2009).
pneumonia (3 papers, 2017 to 2021). An acute, acute and chronic, or chronic inflammation focally or diffusely affecting the lung parenchyma, caused by an infection in one or both of the lungs (by bacteria, viruses, fungi, or mycoplasma.). "In conclusion, this study demonstrates that plasma NPC2 undergoes an upregulation in pneumonia and a further increase in sepsis, possibly resulting from renal dysfunction." (PMID 33723331, 2021). "Documentation of these mutations with phenotypic presentation has become obligatory as commonly occurring bronchitis/pneumonia with liver involvement and failure to thrive are likely to mimic NPC2." (PMID 28095804, 2017). "Our data show a significant accumulation of NPC2 in the plasma of pneumonia and sepsis patients." (PMID 33723331, 2021). "Thus, we subsequently determined NPC2 concentration in plasma from healthy subjects, pneumonia patients and sepsis patients with comorbid pneumonia; and analyzed the association of plasma NPC2 with organ dysfunction and prognosis of sepsis patients." (PMID 33723331, 2021). "To fully characterize the association of plasma NPC2 with sepsis, we determined the concentration of NPC2 in the plasma from healthy individuals, patients of community-acquired pneumonia (CAP), and sepsis patients with comorbid pneumonia (SWP)." (PMID 33723331, 2021). "Compared with pneumonia patients (SOFA_sum = 0 and 1), no significant change in NPC2 concentration occurred in SWP patients until the SOFA score reached 14 or higher." (PMID 33723331, 2021).
thyroid cancer (3 papers, 2023 to 2025). "High NPC2 protein expression has been detected in several cancers, such as breast, colon, and thyroid cancer." (PMID 39690926, 2024). "As a result, NPC2 and ARHGAP36 have been proposed as potential diagnostic and therapeutic targets for thyroid cancer." (PMID 38129369, 2023). "Furthermore, the knockdown of NPC2 was shown to significantly promote thyroid cancer cell apoptosis." (PMID 38129369, 2023).
virus infection (3 papers, 2021 to 2024). "Taken together, virus infections appear to affect the expression of several NPC2 genes, indicating their potential role in arboviral transmission." (PMID 38338961, 2024). "Together, these experiments show that NPC2 enhances an early stage in viral infection prior to replication." (PMID 35867410, 2022). "Here, we found that NPC2 protein interacts with viral envelope glycoprotein gp64 to promote virus infection through the intracellular cholesterol transport pathway." (PMID 35867410, 2022). "Similarly, we knocked out NPC2 and found that the early stage of viral infection was inhibited, which affected the efficiency of viral fusion in the endosome." (PMID 35867410, 2022). "Taken together, our results suggest that NPC2 protein incorporated into viral particles may facilitate viral infection through promoting the interaction of BmNPV and NPC1 in the endosome, thus enhancing viral fusion and escape from endosomes." (PMID 35867410, 2022). "Therefore, we investigated the mechanism of NPC2 protein to promote virus infection." (PMID 35867410, 2022). "Previous research results did not provide direct evidence that NPC2 protein is related to virus infection." (PMID 35867410, 2022). "For this purpose, BmE cells and NPC2-treated cells were infected with BmNPV (MOI, 0.5) for 72 h; we then quantified viral gene copy numbers by quantitative PCR and found that BmNPC2 promotes virus infection." (PMID 35867410, 2022). "Previous studies have identified NPC1 and NPC2 as important host factors for viral infection in insect cells, although their exact role in viral infection has not yet been determined." (PMID 35867410, 2022). "Also, editing of NPC1, NPC2, or TFE3 that functions in endolysosomes had a negligible impact on Sfull virus infection." (PMID 33574281, 2021). "The addition of NPC2 protein in the NPC1 knockout cell lines did not promote virus infection." (PMID 35867410, 2022). "Knockout of NPC2 reduced the fusion efficiency of the viral membrane and host endosomal membrane, and the expression of NPC2 protein in the NPC1 knockout cell line did not promote virus infection." (PMID 35867410, 2022).
alveolar proteinosis (2 papers, 2017 to 2021). "Our study demonstrates that NPC2 can present in early years of life with pulmonary complications like alveolar proteinosis and hepatosplenomegaly or hepatomegaly due to mutation in NPC2 gene." (PMID 28095804, 2017). "In addition, reduced expression of NPC2 is associated with alveolar proteinosis and macrophage accumulation in the lung, liver and spleen, in human as well as rodents, suggesting that NPC2 may play an important role in the pathophysiology of multiple tissues/organs." (PMID 33723331, 2021).
Azoospermia (2 papers, 2022 to 2023). Absence of any measurable level of sperm,whereby spermatozoa cannot be observed even after centrifugation of the semen pellet. "Samples from patients with azoospermia and samples from fertile men were analyzed by 2-D gel electrophoresis and NPC2 was found in all the samples obtained from men with NOA while it was not present in the samples obtained from men with OA." (PMID 37568830, 2023). "From the diagnostic point of view, proteins such as NPC2 or the CRISP1 glycoprotein are very interesting, both produced in epididymis and potential markers of azoospermia." (PMID 37568830, 2023). "For detection of the type of azoospermia, proteins can be used individually (L-PGDS, NPC2 or ECM1) or, more effectively, in a combination of two or more detected proteins with different expressions in the male genital tract." (PMID 37568830, 2023).
dementia (2 papers, 2016 to 2022). Loss of intellectual abilities interfering with an individual's social and occupational functions. "Pathogenic variants of the NPC1 or NPC2 genes yield highly variable phenotypes with a time course that ranges from fetal onset (i.e., hydrops fetalis) to progressive dementia in adults." (PMID 27549128, 2016). "The results of our study demonstrated that heterozygous mutations of NPC1 and NPC2 genes could contribute to dementia plus, at least in a subset of Calabrian patients." (PMID 36140389, 2022).
Gaucher disease (2 papers, 2017 to 2024). Gaucher disease (GD) is a lysosomal storage disorder encompassing three main forms (types 1, 2 and 3), a fetal form and a variant with cardiac involvement (Gaucher disease - ophthalmoplegia - cardiovascular calcification or Gaucher-like disease). "In 2 cases where the biochemical diagnosis of Gaucher disease was made due to the low levels of beta-glucosidase enzyme in leukocytes, the smMIP based assay detected pathogenic variant in the NPC1 and NPC2 gene in either case." (PMID 38730490, 2024).
Hepatosplenomegaly (2 papers, 2015 to 2017). Simultaneous enlargement of the liver and spleen. "Since then several studies have shown an association of pulmonary manifestation and hepatosplenomegaly with NPC2." (PMID 28095804, 2017). "The only two patients in the UK cohort who had NPC2 mutations were in this age-at-onset subgroup (patients 54 and 65), both of whom displayed neonatal jaundice and hepatosplenomegaly, as was common among other late-infantile onset patients." (PMID 26666848, 2015). "Present study is the first report of NPC2 from India with primary pulmonary manifestations and hepatosplenomegaly highlighting phenotype-genotype correlation." (PMID 28095804, 2017).
immune deficiency (2 papers, 2020 to 2024). "In invertebrates, evidence shows that NPC-2 proteins may be involved in innate immune signaling pathways, such as the immune deficiency (Imd) pathway." (PMID 32868841, 2020). "Interestingly, the pair NPC1 (AAEL009531) and NPC2 (AAEL001650) is suggested to function together and negatively affect the immune deficiency immune signalling pathway in mosquitos infected with dengue virus serotype 2." (PMID 38338961, 2024).
lipidosis (2 papers, 2013 to 2017). "Our results, on the other hand, demonstrated that alveolar lipidosis and other pathological changes were at least as severe in the NPC1 mutant mouse compared to the NPC2 hypomorph mouse." (PMID 23843985, 2013).
liver disease (2 papers, 2013 to 2021). "Since liver is the main source of plasma and biliary NPC2, we next examined whether serum NPC2 level can be used as a novel biomarker for liver diseases." (PMID 24147030, 2013).
lung diseases (2 papers, 2013 to 2021). "In addition, NPC2 expression was significantly lower in other lung diseases, except for active sarcoidosis." (PMID 34685683, 2021). "The NPC1 and NPC2 pulmonary diseases were compared to determine whether any pathologic characteristics differed between them." (PMID 23843985, 2013). "Our study, using histological, immunological and biochemical procedures, demonstrates that the absence of NPC1 and NPC2 proteins in the lungs of mutant mice on a BALB/c background results in lung disease." (PMID 23843985, 2013).
Splenomegaly (2 papers, 2015 to 2017). Abnormal increased size of the spleen. "While several patients in this cohort had high NP-C SI scores as well as clinical signs associated with NP-C (VSGP and splenomegaly), genetic analyses did not reveal any NPC1 or NPC2 mutations." (PMID 28222799, 2017). "NP-C needs to be considered in the differential diagnosis of isolated splenomegaly in adults without neurological and neuropsychiatric manifestations and, in the absence of elevated oxysterols, molecular analysis of NPC1 and NPC2 genes should be pursued." (PMID 26937389, 2015).
Tangier disease (2 papers, 2013 to 2020). "When we measured levels of NPC1 and NPC2 in Tangier disease cells by western blotting we found there to be variation between the patients." (PMID 31707734, 2020). "Mutations in hexaminidase A, hexaminidase B, Niemann-Pick type C2, and ATP-binding cassette transporter A1 (ABCA1) cause Tay-Sachs, Sandhoff disease, Niemann-Pick type C2 (NPC2), and Tangier disease, respectively." (PMID 24058676, 2013).
age-related maculopathies (1 paper, 2025). "A deficiency in NPC2 has previously been associated with age-related maculopathies." (PMID 40221802, 2025).
arbovirus infection (1 paper, 2024). A viral infection that is transmitted by an arthropod. "We studied Niemann–Pick Type C2 (NPC2) proteins, a superfamily of saliva proteins that play an important role in arbovirus infections." (PMID 38338961, 2024). "NPC2 genes are differentially expressed in both the midgut and the salivary gland during CHIV, DENV2 and ZIKV arbovirus infections." (PMID 38338961, 2024).
aspiration pneumonia (1 paper, 2016). "Pulmonary infiltrates, which are more often associated with a diagnosis of NP-C2 (due to mutations in the NPC2 gene) or with aspiration pneumonia in late-stage progressive disease, were unexpectedly common amongst all NP-C cases (13 %)." (PMID 27449637, 2016).
asthma (1 paper, 2023). "The GSEA analysis showed that high NPC2 expression was significant associated (P < 0.05) with asthma, cytokine-cytokine receptor interaction, drug metabolism other enzymes, natural killer cell mediated cytotoxicity, primary bile acid biosynthesis, and systemic lupus erythematosus." (PMID 38001127, 2023).
astrocytoma (1 paper, 2009). "In cultured human astrocytoma cells (CCF-STTG1), both haloperidol and clozapine significantly up-regulated ApoE, NPC1 and NPC2 at 24 hours of incubation (n = 3)." (PMID 19715613, 2009).
atherosclerosis (1 paper, 2020). A disease characterized by the build-up of fatty material and calcium deposition in the arterial wall resulting in partial or complete occlusion of the arterial lumen. "In this list, two novel biomarker candidates, NPC2 and IGFBP7, were identified along with several proteins, such as THBS1, that have been reported to be involved in atherosclerosis or AA." (PMID 32286426, 2020). "Although NPC2 is known to bind cholesterol and promote cholesterol transport, in conjunction with NPC1, its contribution to atherosclerosis has not yet been established." (PMID 32286426, 2020).
breast tumor (1 paper, 2013). "Among the 23 pairs of breast tumor and normal tissues tested, 18 (78%) of the tumor tissues showed higher NPC2 expression levels than their normal tissues (p<0.0001)." (PMID 24147030, 2013).
cholestatic jaundice (1 paper, 2014). "This was an infant with cholestatic jaundice without confirmed diagnosis, who was later excluded as NP-C or a heterozygote of NPC1/NPC2 gene by molecular analysis." (PMID 24915861, 2014).
chronic obstructive pulmonary disease (1 paper, 2023). A chronic and progressive lung disorder characterized by the loss of elasticity of the bronchial tree and the air sacs, destruction of the air sacs wall, thickening of the bronchial wall, and mucous accumulation in the bronchial tree. "In addition to Niemann–Pick Type C2 (NPC2) disease, NPC2 is involved in chronic obstructive pulmonary disease (COPD)." (PMID 37623890, 2023).
fatty liver disease (1 paper, 2013). A reversible condition wherein large vacuoles of triglyceride fat accumulate in liver cells via the process of steatosis. "Recently, we showed that NPC2 acts coordinately with glycine N-methyltransferase to regulate hepatic cholesterol homeostasis and fatty liver disease progression." (PMID 24147030, 2013).
fibrosis (1 paper, 2018). the formation of excess fibrous connective tissue in an organ or tissue in a reparative or reactive process. "Livers of patients with fibrosis (all F1 apart from 1 patient whom was F2) had up-regulations of PPARG (20%), INSIG1 (39%), SRB1 (11%), NPC1 (13%), and NPC2 (30%) (all P < 0.05)." (PMID 29522534, 2018).
glaucoma (1 paper, 2018). Increased pressure in the eyeball due to obstruction of the outflow of aqueous humor. "LDL and HDL are two key nodes in the network, and APOC3, NPC2, LDL, and HDL are connected to cholesterol, strengthening the evidence that lipid metabolism pathway proteins are upregulated in AH from glaucoma patients." (PMID 29847670, 2018).
goiter (1 paper, 2011). Enlargement of the thyroid gland usually caused by lack of iodine in the diet, hyperthyroidism, or thyroid nodules. "In fact, any form of papillary projections, such as intrafollicular papillary projection in goiter tissues and colon polyps expressed NPC2 protein." (PMID 21253586, 2011).
gout (1 paper, 2020). A condition characterized by painful swelling of the joints, which is caused by deposition of urate crystals. "Regarding RECK and NPC2, rs186201319 and rs539604468 confounded the relationship between RECK methylation and gout and between NPC2 methylation and gout, respectively." (PMID 32630231, 2020).
intraductal breast papilloma (1 paper, 2013). A benign papillary neoplasm that arises anywhere in the ductal system of the breast. "Since strong expression of NPC2 is observed in human intraductal breast papilloma, colon polyps, lung papillary carcinoma and ovarian fimbria, NPC2 protein may contribute to papillae formation." (PMID 24147030, 2013).
ischemia (1 paper, 2024). A hypoperfusion of the BLOOD through an organ or tissue caused by a PATHOLOGIC CONSTRICTION or obstruction of its BLOOD VESSELS, or an absence of BLOOD CIRCULATION. "NPC2 and Nceh1 expression in edge regions was up‐regulated after ischemia and significantly higher than in core regions." (PMID 39252446, 2024).
kidney tumor (1 paper, 2013). "Among 33 pairs of kidney tumor and normal tissues, 31 (94%) tumor tissue samples had a much lower NPC2 expression than the equivalent normal tissue sample (p<0.0001)." (PMID 24147030, 2013).
liver dysfunction (1 paper, 2021). "In fact, plasma NPC2 exhibited a moderate, and positive, association with liver dysfunction in sepsis patients (i.e. increases in total bilirubin and direct bilirubin in plasma)." (PMID 33723331, 2021).
malnutrition (1 paper, 2021). Inadequate nutrition resulting from poor diet, malabsorption, or abnormal nutrient distribution. "The single gene biomarkers NPC2 and BATF2 were very effective in distinguishing between TB and LTBI in malnutrition." (PMID 33482742, 2021).
melanoma (1 paper, 2017). A malignant, usually aggressive tumor composed of atypical, neoplastic melanocytes. "Presence of the polar amino group in both compounds, led to similar predicted binding interactions (hydrophobic and H-bond contacts) in both NPC1 and NPC2 active sites, as evidenced by similar anti-melanoma activity of 4a." (PMID 28423677, 2017).
metabolism (1 paper, 2014). "The gene with the highest overexpression index in the control group codes for a Niemann-Pick type protein (NPC2), that is, genes involved in cholesterol metabolism-related syndromes and diseases (another npc2-type gene was found slightly overexpressed in the KD bees)." (PMID 25566327, 2014).
Multiple Organ Failure (1 paper, 2021). A progressive condition usually characterized by combined failure of several organs such as the lungs, liver, kidney, along with some clotting mechanisms, usually postinjury or postoperative. "Based on these results, we conclude that the increase in plasma NPC2 in sepsis patients is associated with multiple organ failure, possibly results from a deficiency in renal clearance, and may serve as a prognostic marker for sepsis." (PMID 33723331, 2021). "The significant increase of NPC2 in septic plasma occurs in association with multiple organ failure, and may serve as a prognostic marker for sepsis." (PMID 33723331, 2021).
neuroblastoma (1 paper, 2016). Neuroblastoma (NB) is the most common solid, extracranial childhood tumor. "Here, we show that CtsB/L inhibition in CHO and in human neuroblastoma SH-SY5Y cells as well as CtsB and CtsL genetic depletion also affects NPC1 and/or NPC2 and causes their sequestration and accumulation of intracellular free cholesterol." (PMID 27902765, 2016).